FOXP1 (forkhead box P1)
Diseases named in the same sentence as FOXP1 in open-access papers (continued):
Sharing a sentence is not in itself a finding about the gene and the disease.
Myocardial fibrosis (3 papers, 2021 to 2024). "Additionally, the endothelial cell‐derived transcription factor Forkhead box protein P1 (Foxp1) promotes the expression and secretion of TGF‐β1, thus promoting the progression of myocardial fibrosis." (PMID 37799807, 2023).
myocardial infarction (3 papers, 2022 to 2026). Gross necrosis of the myocardium, as a result of interruption of the blood supply to the area, as in coronary thrombosis. "This study demonstrates that Foxp1 is downregulated at border zone cardiomyocytes of both neonatal apical resection and adult myocardial infarction." (PMID 39899693, 2025). "Echocardiography results showed that the left ventricular ejection fraction of the FoxP1 knockdown group was lower than that of the myocardial infarction group." (PMID 36088337, 2022). "More importantly, FoxP1 has anti-inflammatory and anti-atherosclerotic effects in the control of coronary thrombosis and myocardial infarction." (PMID 36088337, 2022). "Additionally, FOXP1 promoted angiogenesis in adult rats following myocardial infarction." (PMID 41596522, 2026). "This study aims to investigate the angiogenic role of FoxP1 in a rat model of myocardial infarction (MI)." (PMID 36088337, 2022).
preeclampsia (3 papers, 2021 to 2024). Preeclampsia is a hypertensive disorder of pregnancy that is characterized by new-onset hypertension with proteinuria presenting after 20 weeks of gestation, and depending on mild or severe forms may initially present with severe headache, visual disturbances, and hyperreflexia. "Specifically, predicted stromal cell dS2-specific PRDM1 and FOXP1 targets were enriched in preeclampsia downregulated stromal genes." (PMID 39090334, 2024). "Two of these – namely DDX39A and LMBR1L – potentially contribute to immune responses and inflammation, whereas FOXP1 and FOXC1 have been linked to preeclampsia and gestational diabetes, respectively." (PMID 36840948, 2023). "We found that for stromal cells, the predicted dS2 and dS3 specific regulon targets were enriched with preeclampsia downregulated genes, particularly regulon targets predicted for PRDM1 (LOP down p = 1.75 × 10–18, 21-fold) and for FOXP1 (LOP down, p = 3.8 × 10–14, 9.1-fold)." (PMID 39090334, 2024).
serous ovarian carcinoma (3 papers, 2010 to 2016). "On the contrary, the prognosis of patients with chemoresistance was very poor when FOXP1 was up-regulated in stage III serous ovarian carcinoma, suggesting that FOXP1 may function as an oncogene." (PMID 26654944, 2016). "The function of FOXP1 in serous ovarian cancer remains unclear." (PMID 20969748, 2010).
vitiligo (3 papers, 2012 to 2024). Generalized well circumscribed patches of leukoderma that are generally distributed over symmetric body locations and is due to autoimmune destruction of melanocytes. "Recently, a number of genes which play a role in vitiligo susceptibility, including HLA, PTPN22, NALP1, XBP1, FOXP1, IL2RA have been tested for genetic association with vitiligo." (PMID 23284977, 2012).
Achalasia (2 papers, 2021). A disorder of esophageal motility characterized by the inability of the lower esophageal sphincter to relax during swallowing and by inadequate or lacking peristalsis in the lower half of the body of the esophagus. "NOS1 mutations were identified in patients diagnosed with autism and achalasia, resulting into eating and drinking problems, and FOXP1 mutations were found in patients with ASD symptoms, language impairment, anxiety, and various GI complaints." (PMID 32461615, 2021). "Achalasia and delayed GI transit caused by impaired function of the lower esophageal sphincter and decreased motility, leading to eating and drinking problems and constipation, was observed in Foxp1+/− mice." (PMID 32461615, 2021). "Altered motility and achalasia has been observed in Foxp1+/− mice." (PMID 33608531, 2021).
acute lymphoblastic leukemia (2 papers, 2016 to 2025). Leukemia with an acute onset, characterized by the presence of lymphoblasts in the bone marrow and the peripheral blood. "FOXP1 also facilitated the proliferation of pre–B acute lymphoid leukemia cells and enhanced their resistance to chemotherapeutic agents." (PMID 40672953, 2025). "The Ikaros-Foxp1 interaction is abolished by deletion of this region, which corresponds to the IK6 isoform that is commonly associated with high-risk acute lymphoblastic leukemia (ALL)." (PMID 27588474, 2016). "Further analysis using the Hemap database, which contains microarray-based transcriptomic profiles of various hematologic malignancies, showed that FOXP1 expression (log2 normalized intensity) was markedly elevated in patient samples of pre-B cell acute lymphoblastic leukemia (pre-B-ALL) and AML." (PMID 40672953, 2025).
Alzheimer disease (2 papers, 2024 to 2025). A progressive, neurodegenerative disease characterized by loss of function and death of nerve cells in several areas of the brain leading to loss of cognitive function such as memory and language. "Genes such as SLC1A3, FOXP1, and MS4A6A, associated with inflammatory response, and microglia in aging and Alzheimer's disease, had positive average coefficients among the microglia clock feature genes." (PMID 40878446, 2025).
apraxia (2 papers, 2012 to 2022). Apraxia is a neurological disorder characterized by the inability to perform tasks or movements, despite having the desire and physical ability to perform them. "To date, the FOXP1 gene has been linked exclusively to neurodevelopmental speech disorders, while our study highlights its possible relevance for adult-onset progressive apraxia of speech, which guarantees further study." (PMID 36553628, 2022). "Although articulation problems have been described in some patients with FOXP1 disruption, orofacial dyspraxia has not been diagnosed so far, neither have any FOXP1 variants been identified in the small DVD patient cohort." (PMID 22736078, 2012).
autoimmune disease (2 papers, 2019 to 2022). A disorder resulting from loss of function or tissue destruction of an organ or multiple organs, arising from humoral or cellular immune responses of the individual to their own tissue constituents. "Alternatively, through the inhibition of Tfh differentiation, the reduction of FOXP1 levels may help alleviate autoimmune diseases driven by abnormal B-cell responses." (PMID 36268015, 2022).
breast invasive ductal carcinoma (2 papers, 2018 to 2023). "The aims of this study were to investigate FOXP1 expression patterns in invasive ductal carcinoma (IDC), ductal carcinoma in situ (DCIS), atypical ductal hyperplasia (ADH) and usual ductal hyperplasia (UDH), and to analyze the clinicopathological relevance of C-FOXP1 and its prognostic value in IDC." (PMID 29848352, 2018).
Cachexia (2 papers, 2021 to 2025). Severe weight loss, wasting of muscle, loss of appetite, and general debility related to a chronic disease. "Importantly, FoxO1 is consistently identified as a cachexia‐associated gene increased in muscle of cancer patients, and we show that increased levels of FoxP1 are also associated with cachexia in cancer patients." (PMID 33527776, 2021). "Here, we identify FoxP1 as a key disruptor of the skeletal-muscle clock in response to cancer that reprograms circadian patterns of gene expression at cachexia onset." (PMID 40349340, 2025). "Our findings identify that cancer-induced FoxP1 disrupts and rewires circadian patterns of gene expression in skeletal muscle that may contribute to the development of cachexia." (PMID 40349340, 2025). "In support of this, over‐expression of FoxP1 in skeletal muscles led not only to skeletal muscle wasting but also body wasting and was often coincident with fat wasting, which are all features of cachexia observed in cancer patients and tumour‐bearing mice." (PMID 33527776, 2021). "We thus measured the protein expression of FOXP1 in muscle biopsies from non‐cancer controls and patients with PDAC—a cancer type displaying one of the highest incidences of cachexia." (PMID 33527776, 2021).
cholangiocarcinoma (2 papers, 2024 to 2025). A carcinoma that arises from the intrahepatic biliary tree (intrahepatic cholangiocarcinoma) or from the junction, or adjacent to the junction, of the right and left hepatic ducts (hilar cholangiocarcinoma). "Since the Wnt/β-catenin signaling pathway was previously reported as a vital regulatory factor in cholangiocarcinoma, the key pathway-related proteins, including Wnt3a, phosphorylated GSK3β, and β-catenin, were detected in HCCC-9810 cells after FOXP1 overexpression or knockdown." (PMID 38279090, 2024).
colitis (2 papers, 2018 to 2019). Inflammation of the colon. "Mice with Foxp1-deficient Treg cells developed spontaneous inflammatory disease with age; they also had more severe inflammatory disease in colitis and experimental autoimmune encephalomyelitis (EAE) models." (PMID 31125332, 2019). "Consistently, we found that the recipient mice transferred with Foxp1-deficient iTreg cells developed more severe colitis, indicated by the greater body weight loss and more IFNγ- or IL-17A–producing T cells in the colons." (PMID 31125332, 2019). "In order to determine the relative contributions of impaired iTreg homeostasis versus functional incompetence of tTreg cells in gut-associated inflammation upon Foxp1 deletion, we next employed a cell transfer model of colitis." (PMID 30367168, 2018). "Thus Treg-specific deletion of Foxp1 rendered mice with enhanced susceptibility to a physiologically relevant experimental model of colitis." (PMID 30367168, 2018). "The mice with Treg-specific depletion of Foxp1 develop spontaneous inflammatory disease and are more susceptible to dextran sulfate sodium (DSS)-induced colitis and experimental autoimmune encephalomyelitis (EAE)." (PMID 31125332, 2019). "By employing a co-transfer model of colitis induction, however, we observed that unlike Foxp1-deficient in vitro-differentiated iTreg cells, the Foxp1-deficient tTreg cells remained largely protective compared to their wild-type counterparts." (PMID 30367168, 2018). "Mice with Foxp1 deletion in Treg cells spontaneously developed inflammatory disease, and DSS-induced colitis and EAE were more severe in Foxp1f/fFoxp3Cre mice." (PMID 31125332, 2019).
congenital heart defect (2 papers, 2019 to 2024). "In this study, we observed a strong downregulation of ADAR2 and FOXP1 at the RNA level in PBMCs of congenital heart defect patients." (PMID 31039163, 2019).
dilated cardiomyopathy (2 papers, 2019 to 2023). Cardiomyopathy which is characterized by dilation and contractile dysfunction of the left and right ventricles. "This implies that the decrease in ADAR2 and FOXP1 is associated with dilated cardiomyopathy." (PMID 31039163, 2019).
endometrial adenocarcinoma (2 papers, 2015 to 2018). "Loss of FOXP1 nuclear expression is the most striking observation, and cytoplasmic expression is noted more frequently in endometrial adenocarcinoma according to the literature." (PMID 29848352, 2018). "Recently, one report presents that exclusive cytoplasmic localization of Foxp1 in endometrial adenocarcinoma is linked with deep myometrial invasion mediated by HIF-1α, which is an essential player in cellular and systemic responses to hypoxia." (PMID 26171970, 2015).
endothelial dysfunction (2 papers, 2025 to 2026). In vascular diseases, endothelial dysfunction is a systemic pathological state of the endothelium (the inner lining of blood vessels) and can be broadly defined as an imbalance between vasodilating and vasoconstricting substances produced by (or acting on) the endothelium. "Conversely, the overexpression of FOXP1 exhibits an opposite trend, suggesting that FOXP1 can delay vascular endothelial cell senescence and alleviate endothelial dysfunction." (PMID 41355963, 2026). "SA-β-gal staining and tube formation assays indicated that overexpression of FOXP1 significantly delayed endothelial senescence and alleviated endothelial dysfunction." (PMID 41355963, 2026). "FOXP1 has been reported to protect against inflammation and endothelial cell damage, with overexpression reducing vascular inflammation, endothelial inflammasome activation, and endothelial dysfunction." (PMID 39319864, 2025).
hyperglycaemia (2 papers, 2021 to 2024). "Interestingly, abnormal elevation of hepatic glucose production is known to contribute to fasting hyperglycemia in T2D, and in a diabetic murine model increased gluconeogenesis promoted by FOXO1 seems to be ascribable to decreased FOXP1 expression in the liver." (PMID 33664777, 2021).
idiopathic pulmonary fibrosis (2 papers, 2022 to 2025). Idiopathic pulmonary fibrosis (IPF) is a nonneoplastic pulmonary disease that is characterized by the formation of scar tissue within the lungs in the absence of any known cause. "Those with the T allele instead of the C allele for rs1499894, or the G allele instead of the A allele for rs35480566 had increased FoxP1 mRNA levels in transcriptomic data, higher FEV1 and FVC, and reduced odds of being diagnosed with idiopathic pulmonary fibrosis." (PMID 36221131, 2022). "Most of the significantly enriched TFs related to pulmonary fibrosis included STAT3, FOXP1, JUNB, ATF3, FosL2, BATF, Fra2 and AP‐1." (PMID 40464702, 2025).
intellectual disability syndrome (2 papers, 2022 to 2023). "This prompted clinicians to define a separate NDD, FOXP1-related intellectual disability syndrome." (PMID 36257692, 2022).
intrahepatic cholangiocarcinoma (2 papers, 2024 to 2025). A carcinoma that arises from the intrahepatic bile duct epithelium in any site of the intrahepatic biliary tree. "However, the role of FOXP1 in intrahepatic cholangiocarcinoma (ICC) has not been previously reported." (PMID 38279090, 2024).
keloid (2 papers, 2023 to 2025). An irregularly shaped, elevated mark on the skin caused by deposits of excessive amounts of collagen during wound healing. "By predicting the major TFs upstream of the identified SE-associated genes, it was discovered that FOSL2, BACH2, and FOXP1 were not only highly enriched in keloid fibroblasts but also significantly upregulated in keloids." (PMID 40702440, 2025). "The results of the FOXP1-Cut&Tag experiment in keloid fibroblasts revealed that FOXP1 is associated with the SEs of SERPINH1, MMP14, COL5A1, COL16A1, and SPARC, all of which exhibited significant signal enrichment in their SE regions." (PMID 40702440, 2025). "To confirm the relationship between FOXP1 and SE-associated genes in keloid, we knocked down FOXP1 with shRNAs in keloid fibroblasts." (PMID 40702440, 2025). "In addition, we investigate the landscape of SE-associated genes in keloid fibroblasts and explore the role of FOXP1 as a core transcriptional regulator in this context." (PMID 40702440, 2025). "We also found that FOSL2, BACH2, and FOXP1 were significantly highly expressed in the keloid group, and the results were as shown in the heatmap." (PMID 40702440, 2025). "On the basis of cell migration and invasion assays, we observed that knockdown of FOXP1 significantly suppresses the migration and invasion capabilities of keloid fibroblasts." (PMID 40702440, 2025). "The upregulation of FOXP1 mRNA and protein levels in keloid fibroblasts was further confirmed by western blot and qPCR analyses." (PMID 40702440, 2025). "We plan to verify the upstream regulators of FOXP1 in subsequent work to further refine the understanding of FOXP1 in keloids and other fibrous diseases." (PMID 40702440, 2025). "In keloid tissues, the elevated expression of FOXP1 contributes to the persistence and proliferation of fibroblasts, bypassing cellular senescence mechanisms that typically limit tissue overgrowth." (PMID 40702440, 2025). "According to target gene enrichment analysis of FOXP1 in keloid fibroblasts, FOXP1 primarily regulates pathways related to cancer and the MAPK signaling pathway." (PMID 40702440, 2025). "Our in vitro experiments have demonstrated the ability of FOXP1 knockdown to inhibit the migration and invasion of keloid fibroblasts and collagen formation." (PMID 40702440, 2025). "On the basis of the results of CRC analysis, FOXP1 was further identified as a core TF and was specifically upregulated in keloid and keloid fibroblasts." (PMID 40702440, 2025). "Based on our group’s published circRNA sequencing analysis and qRT-PCR validation in expanded samples, circFoxp1 (derived from the 8–12 exon region of the FOXP1 gene) was markedly upregulated in human keloid tissues." (PMID 37993257, 2023). "Because the function of FOXP1 in chronic fibrosis of the skin is unknown, we performed the relevant phenotype identification to investigate the effect of FOXP1 on keloid formation." (PMID 40702440, 2025). "By utilizing keloid sample data for TF analysis and target gene prediction, we identified three potential master TFs (FOXP1, FOSL2, and BACH2) that may regulate the expression of these five SE-associated genes in keloids." (PMID 40702440, 2025). "Additionally, we discovered that FOXP1 functions as a core TF promoting fibrosis and anti-senescence during keloid progression." (PMID 40702440, 2025). "Additionally, downregulation of FOXP1 markedly inhibits the gelatin contraction ability of keloid fibroblasts." (PMID 40702440, 2025). "To explore whether FOXP1 mediates senescence regulation in fibrosis, we found that knockdown of FOXP1 in keloid fibroblasts simultaneously resulted in accelerated senescence, as characterized by increased SA-β-gal activity and increased expression of the senescence markers p16 and p21." (PMID 40702440, 2025). "In agreement with the high-throughput sequencing results, circFoxp1 was significantly upregulated in the keloid tissues, whereas the Foxp1 expression level did not change." (PMID 37993257, 2023).
keloid (continued). "This non-senescent state, maintained by FOXP1, promotes the excessive deposition of ECM proteins, leading to the characteristic thickening and scarring observed in keloids." (PMID 40702440, 2025).
Lobular Carcinoma (2 papers, 2007 to 2022). "Overexpressed genes in lobular carcinomas were the tumor suppressor FOXP1 and another transcription regulator MID1." (PMID 17389037, 2007).
multiple sclerosis (2 papers, 2020 to 2022). A progressive autoimmune disorder affecting the central nervous system resulting in demyelination. "The IMSGC assessed two sets of GWAS data and identified rs9828629/FOXP1 (P = 1.9E-10, odds ratio [OR] = 1.08) as an immune-related risk variant linked to MS." (PMID 32719717, 2020). "The maximum reduction of Dnajb1/Dnajb2/Foxp1/Tnfsf14 network was observed when Multiple sclerosis rats were treated with exercise training and 100 mg/kg Royal jelly (ET-RJ100), but the relative expression of the Hspa4 significantly increased." (PMID 35676653, 2022). "The maximum reduction of the Dnajb1/Dnajb2/Foxp1/Tnfsf14 network was observed when Multiple sclerosis rats were treated with exercise training and 100 mg/kg Royal jelly (ET-RJ100), but the relative expression of the Hspa4 significantly increased." (PMID 35676653, 2022). "Numerous large-scale GWASs revealed more than 200 susceptible loci of MS, such as HLA, forkhead box protein P1 (FOXP1), IQCB1, SLC9A9, and CD226." (PMID 32719717, 2020).
ovarian tumor (2 papers, 2019 to 2025). "Deletion of FOXP1 in activated murine T cells impairs antitumor activity in B16-CD19 mice, while Foxp1–/– T cells have better effects in an ovarian tumor model." (PMID 40693464, 2025). "The level of miR-152 and FOXP1 was inversely correlated in grade 3 and 4 ovarian tumor tissues." (PMID 31214170, 2019).